MIR5008 (microRNA 5008)
Synonyms: hsa-mir-5008
Gene: MicroRNA gene on chromosome 1 (227,941,590 to 227,941,683, reverse strand). Ensembl gene ENSG00000264483.
Homologues: Orthologues: chimpanzee MIR5008 (100% identical).